ADAM10 (ADAM metallopeptidase domain 10)
Diseases named in the same sentence as ADAM10 in open-access papers (continued):
Sharing a sentence is not in itself a finding about the gene and the disease.
tumor (continued). "However, neither Cluxton nor our group detected enhanced ADAM10 (or ADAM17) transcription in tumor cells upon exposure to platelets (or platelet releasate)." (PMID 32117229, 2020). "When using growth factors as a stimulus, anti-ADAM10 or anti-ADAM17 significantly increased GSC migration, but this was not true for NSCs suggesting an inherent difference in cellular response to metalloproteinase inhibition between tumour and non-tumour stem cells." (PMID 27541285, 2017). "In combination with ADAM10 and ADAM17 inhibition decreasing GSC proliferation, these new therapeutic targets may provide a mechanism for depletion of the tumourigenic stem cell pool that seeds the tumour whilst sparing native neural stem cells." (PMID 27541285, 2017). "Therefore, the inhibition of ADAM10 induced by 5-FU could one of the mechanisms utilized for inducing and maintaining MICA expression on tumor cells." (PMID 27385218, 2016). "Furthermore, it is known that expression of ADAM10 is also regulated by β-catenin/TCF-dependent signaling, thereby implying a positive feed-back regulation of tumor growth by this protease and emphasizing the importance of inhibiting ADAM10 in inhibition of cancer progression.." (PMID 26440150, 2015). "In this study, we showed that miR-494 directly binds to the 3′UTR regions of Bmi1 and ADAM10 in HNC-TICs, thus represses the tumorigenecity and TIC properties such as sphere formation capability, CD44 and ALDH1 expression, clonogenic ability, and in vivo tumor initiation incident." (PMID 26090866, 2015). "The results of the present study demonstrated that downregulation of ADAM10 resulted in the suppression of TCA8113-cell proliferation and a significant reduction in cellular invasion and migration, which indicated that ADAM10 was involved in processes of tumor development and metastasis." (PMID 25333745, 2015). "Furthermore, the absent staining of TRAP and positive staining of CD31 in multinucleated giant cells suggest that these cells are not osteoclasts, but rather a type of angiogenic tumor cells in which ADAM10/Notch1 signaling is activated." (PMID 24548763, 2014). "Surprisingly, for none of the tumor cell lines tested, stimulation altered ADAM10 surface levels." (PMID 24130797, 2013). "This might indicate that hematopoietic tumor cells display more constitutive ADAM10 as compared to non-hematopoietic cells." (PMID 24130797, 2013). "Notably, components of the EGF signaling network, Adam10, a metallopeptidase that processes EGF, and Grb2, an adaptor protein that binds directly to the EGF receptor, exhibited a greater importance for transgenic than for tumor TFs (blue dots)." (PMID 21464922, 2011). "Either the levels of active ADAM10 were not sufficient in the surgical samples to generate detectable L1 ectodomain, or L1 proteolysis was inhibited, possibly by its inclusion in intercellular junctions in the interior of the tumor mass." (PMID 19874583, 2009). "Although dihydrotestosterone modulates the gene expression of ADAM9, ADAM10 and ADAM17 in an androgen-dependent cell line, the expression of the ADAM species in these tumor cell lines may result mainly from the gene regulation associated with transformation of the cells." (PMID 16277668, 2005). "Moreover, ADAM10 sheddase activity was reported to be notably higher in aggressive NSCLC tumours and in exosomes from the blood of NSCLC patients, suggesting its potential as a significant biomarker, despite inconsistent protein expression levels in primary tumours." (PMID 40427200, 2025). "In addition, whether other metalloproteinases are also regulated by HIF-1α to mediate the immune escape of tumor cells from the killing by NK cells, and whether common metalloproteinases (MMP2, MMP9, and ADAM10) are also regulated by factors parallel to HIF-1α, still require further research." (PMID 40563539, 2025).
tumor (continued). "Finally, when we looked at tumor cells and their interaction with endothelial cell monolayers, we found increased transendothelial migration of MDA-MB-231 cells through irradiated endothelia that could be reduced to baseline levels when inhibiting ADAM10." (PMID 31619190, 2019). "Meanwhile, serum levels of ULBP2 was positively correlated with ADAM10 expression shown by immunohistochemistry, suggesting that gemcitabine may exerts its anti-tumor effect through inhibition of ADAM10 mediated ULBP2 shedding and corresponding enhanced NKG2D-mediated tumor elimination." (PMID 27602753, 2016). "Given the fact that these tumor cells also coexpress ADAM10 and activated Notch1, ADAM10/Notch1 signaling might also participate in this process, as recent studies have demonstrated that ADAM10 and Notch1 could promote the migration of a variety of tumor cells, both cooperatively and individually." (PMID 24548763, 2014). "Both ADAM10 and ADAM17 expression correlate with tumor size, metastasis and TNM stage, being a negative prognostic factor." (PMID 37185715, 2023). "Adam10 inhibitor markedly diminished the growth of orthotopic xenograft tumors derived from non-WNT/SHH MB cells and prolonged the lifespan of tumor-bearing mice." (PMID 35273141, 2022). "These MDSCs result from a defect in hematopoiesis, do not overexpress ADAM10, are suppress T cells, express MDSC markers, are heterogeneous, have been extensively characterized, and are not tumor derived." (PMID 32106810, 2020). "Unlike ADAM9, other ADAM family genes ADAM10 and ADAM17 neither differed in their expression levels between HCC tumor tissues and adjacent normal liver tissues, nor showed significant correlation with survival analysis." (PMID 32245188, 2020). "We subsequently examined ADAM10, ADAM17 and ADAM19 expression in the tumour cell and found that while ADAM10/17 are not induced by platelet cloaking, ADAM19 is potently induced." (PMID 30908480, 2019). "Although ADAM17 is able to cleave L1 and CD44, it seems that ADAM10 and not ADAM17 is a major sheddase for these molecules and is responsible for their constitutive shedding also from tumor cells." (PMID 23251384, 2012). "Knockdown of ADAM-10, but not of ADAM-17, abolished MET down-regulation in different tumor cell lines, and compromised the DN30 ability to block MET signaling." (PMID 22973229, 2012). "8C7 selectively bound to tumours in multiple colon PDX lines, irrespective of the initial tumour stage, compared to its low binding to normal colon, and to spleen, which was also recently reported to express ADAM10." (PMID 35804938, 2022). "Interestingly, ADAM10 and ADAM17 are not upregulated in the tumour cell, suggesting a novel and distinct process to regulate NKG2DL cleavage on the tumour cell surface." (PMID 30908480, 2019). "Given that ADAM10 is the primary α-secretase responsible for non-amyloidogenic APP cleavage, understanding how androgen signalling influences this pathway could reveal novel mechanisms of tumour progression." (PMID 41614805, 2025).
cancer (190 papers, 2008 to 2026). A tumor composed of atypical neoplastic, often pleomorphic cells that invade other tissues. "A disintegrin and metalloproteinase domain-containing protein 10 (ADAM10) plays critical roles in various cancer-associated biological events, such as cell multiplication, migration, and metastasis." (PMID 39991567, 2025). "The association between the score of immune invasion and ADAM10 expression in cancer was investigated." (PMID 39211038, 2024). "For example, overexpression of ADAM10 is associated with cancer, most likely as a result of its part in Notch signaling." (PMID 37266401, 2023). "Dysregulation of ADAM10 is also associated with different diseases such as AD, prion disease, and different types of cancer." (PMID 37266401, 2023). "The function of the Tspan15/ADAM10 scissor has started to be investigated using mouse models and cancer cell lines deficient in or over-expressing Tspan15." (PMID 34201472, 2021). "Cancer-associated fibroblast exosomes (CAF-Des) with a heavy load of ADAM10 enhance the motility of cancer cells through GTPase-mediated RhoA and NOTCH signaling." (PMID 34821724, 2021). "NME1 mRNA levels were strongly negatively associated with mRNA levels of ADAM10 in fifteen human cancer types." (PMID 33918324, 2021). "In a related study, ADAM10 was shown to promote in vitro invasion and in vivo tumor formation in mesothelioma, a rare but deadly cancer caused by asbestos exposure." (PMID 34201472, 2021). "In this regard, a number of studies have associated ADAM10 with cleavage of the adhesion molecules N-, E-, and VE-cadherins, thus affecting cancer cell adhesion and migration, and β-catenin signaling." (PMID 32269567, 2020). "ADAM10 (A Disintegrin And Metalloprotease) sheddase targets membrane-bound substrates and its overexpression is associated with progression in several cancers." (PMID 30651596, 2019). "Further support for a fundamental role of miR-710 in cancer derives from the fact that its predicted targets include ADAM10, PDGFRA, and FZD7, which are linked to senescence and stemness." (PMID 31834924, 2019). "ADAM10 has been associated with various cancers owing to its capacity to cleave exo-domain of CXCL16 that correlates with poor survival of OvCa patients." (PMID 30792527, 2019). "ADAM10 is essential for embryonic development and is implicated in cancer, Alzheimer, and inflammatory diseases." (PMID 26668317, 2016). "Increased E-cadherin cleavage and other ADAM10 activities might increase the risk of disease progression in cancer through the promotion of the EMT." (PMID 39497138, 2024). "Both proteins have been implicated in cancer progression in their dependence on ADAM10, making it tempting to speculate that these proteins may contribute to mediating the ADAM10 phenotype in BCP-ALL." (PMID 37422628, 2023). "Pepsin also elicited maturation of ADAM10, a cancer-associated sheddase." (PMID 37175640, 2023). "IP_233890 is an altProt expressed from bicistronic ADAM10 and its association with a subnetwork of transcription factors involved in tumorigenesis may further clarify the role of that gene in cancer." (PMID 36183975, 2023). "Additionally, ADAM10 has also been linked to a variety of human disorders, including neurodegeneration, immune system dysfunction, and cancer." (PMID 36499565, 2022). "Finally, cancer-associated fibroblasts (CAFs) release exosomes highly enriched in ADAM10, thus increasing GTPase RHOA and enhancing cancer cell motility." (PMID 36139610, 2022). "ADAM10 is known to have over 100 substrates including Notch, amyloid precursor protein, cadherins, and growth factors, and is important in health and implicated in diseases such as cancer and Alzheimer’s." (PMID 34201472, 2021). "Additionally, NME1 mRNA levels are strongly negatively associated with mRNA levels of ADAM10 in many human cancers in the TCGA database." (PMID 33918324, 2021).
cancer (continued). "In conclusion, this study indicates that the increased concentration of cell-free exosomes in the blood from BCPs correlated with increased exosomal ADAM-10 expression; however, total blood exosomes contain more malignant neoplasm-associated proteins than plasma exosomes." (PMID 32218180, 2020). "Various members of the ADAM family, including ADAM10, are overexpressed in different types of malignant tumor and may be associated with the biological behavior of the latter." (PMID 25333745, 2015). "Moreover, RT-qPCR analysis of clinical samples revealed co-expression patterns between circSNX5 and ADAM10 transcripts, leading us to hypothesize the effector role of ADAM10 in circSNX5-mediated oncogenesis based on its association with cancer." (PMID 39155279, 2024). "But even if sPrP turns out to be not much more than a bystander, the combination of upregulated ADAM10 and PrP independently described in various cancer types and models could well point towards a diagnostic biomarker potential of sPrP assessable in body fluids." (PMID 35084572, 2023). "Although assessing ADAM10 function in intestinal homeostasis is technically challenging, these observations suggest that ADAM10 is an important and possibly a rate-limiting regulator of Notch signaling during intestinal inflammation and development of colitis-associated cancer." (PMID 36572816, 2023). "However, ADAM10 activity’s association with inflammation and cancers is an important caveat that may have stifled interest or progress in this regard." (PMID 32098349, 2020). "Cancer progression is often associated with the ability to escape immune responses, thus, the association of anti-ADAM10-pro-domain auto-Abs with the favorable clinical outcome of patients at stage III might reflect a more efficient immune response in these patients." (PMID 27517630, 2016). "ADAM10 is a metalloproteinase that, by cleaving the ectodomains of transmembrane proteins, has a widespread effect on cancer cells and their stromal counterparts." (PMID 40075679, 2025). "The elevated expression of ADAM10 in cancer cells intensifies its function as a sheddase, leading to the release of various cell surface proteins, including ligands and receptors belonging to the Notch, Eph, and erbB families." (PMID 39991567, 2025). "More recent studies suggest that ADAM10 contributes to tumorigenesis and progression, suggesting that ADAM10 is a promising new target for cancer therapy." (PMID 39991567, 2025). "ADAM10 is ubiquitously expressed in humans and influences over 40 substrates, of which a portion is involved in cancer proliferation." (PMID 38399697, 2024). "The overexpression of ADAM10 in various cancers and its role in promoting tumor growth make it an attractive target for cancer therapy." (PMID 39457411, 2024). "ADAM10’s role in cancer progression and initiation is less well understood but is thought to be related to increased cell migration and invasion." (PMID 39286024, 2024). "In summary, the combination of ADAM10 targeting and sorafenib for cancer treatment appears to be a promising and viable approach, necessitating future clinical trials for validation." (PMID 39346916, 2024). "Overall, the present study determined ADAM10 expression by AD, CD and m62A, and in AD or CD/ADAM10/LAG3 signaling in cancers, and suggested a potential method for immunotherapy of cancers by targeting ADAM10 using the small molecules AD, CD and m62A." (PMID 39211038, 2024). "MMPs and ADAM, especially MMP-7 and ADAM10, provide apoptotic signals to cancer cells by removing the Fas ligand, a transmembrane receptor Fas, on the cell surface." (PMID 38956273, 2024). "On the other hand, several groups have reported that TEVs produced by different cancer types carry on their surface proteolytically active ADAM10 and ADAM17." (PMID 38542421, 2024).
cancer (continued). "Further, our omics profiling and functional assays revealed that ADAM10 is a critical effector in circSNX5-mediated cancer progression, with circSNX5 maintaining ADAM10 expression by sponging miR-323." (PMID 39155279, 2024). "The present study indicated ADAM10 expression regulation by AD, CD and m62A, and in AD/ADAM10/LAG3 or CD/ADAM10/LAG3 signaling in cancers, suggesting a potential method for immunotherapy of cancers by targeting ADAM10 using the small molecules AD, CD and m62A." (PMID 39211038, 2024). "As results, AD, CD, and m62A inhibited ADAM10 expression in various cancer cell lines, indicating their roles in anti-cancer agents." (PMID 39211038, 2024). "Of these targets, CDCP1 is reportedly associated with PI3K/AKT signaling, CMTM6 is a critical regulator of PD-L1 in a broad range of cancer cells, while UBE2D3 is linked to NF-κB signaling and ADAM10 plays a role in TNF signaling." (PMID 38041015, 2023). "Trop-2 cleavage by ADAM10 exposes a previously inaccessible protein groove in a cancer-specific manner." (PMID 37509383, 2023). "The proteolytic cleavage of NKG2D ligands (NKG2DL) on the cancer cell surface via ADAM10 can impair the recognition of cancer cells by T or NK cells." (PMID 37176052, 2023). "Newer compounds with improved selectivity for ADAM10 have shown promise in preclinical cancer models, with improved patient tolerance." (PMID 37788087, 2023). "The dysregulation of ADAM10 expression and function has important roles in the development of pathological conditions, including AD, autoimmune disorders, and cancer." (PMID 36674432, 2023). "Similar to EGFR antagonists, ADAM10 inhibitors are tested as anti-cancer drugs in randomized clinical trials." (PMID 37967063, 2023). "ADAM10 has been well-characterized as a central sheddase for the shedding of many key receptors and is increased in multiple human cancers." (PMID 37463446, 2023). "Strikingly, a huge amount of published evidence also implicates ADAM10 in various aspects of cancer development and progression." (PMID 35084572, 2023). "Expression analysis of CXCL16 and ADAM10 in BrCa tissues is important because of the CXCL16-CXCR6 ligand-receptor system in cancer development and the ability of ADAM10 to cleave Tm-CXCL16." (PMID 34298782, 2021). "ADAM metallopeptidase domain 10 (ADAM10) is a metalloproteinase that is frequently up regulated in human tumors which triggers cancer initiation, progression, and metastasis." (PMID 34099061, 2021). "ADAM-10 expression was also shown to correlate with invasive growth of different cancers, establishing the protease as a potential therapeutic target." (PMID 33802262, 2021). "ADAM10 also increases the migration potential of cancer cells through the Notch 1 signaling pathway." (PMID 34298782, 2021). "Notch signaling is important in promoting many cancers, so one prediction of the Tspan5/14/ADAM10 Notch activation model is that Tspan5 and Tspan14 will promote such cancers." (PMID 34201472, 2021). "It has been shown to regulate ADAM10 protein expression in renal cancer where it is expressed in 73% of cancer cells." (PMID 34195082, 2021). "Pax2 binds to the promoter of a disintegrin and metalloproteinase domain-containing protein 10 (ADAM10), a metalloprotease that plays a crucial role in cancer progression and metastasis." (PMID 34195082, 2021). "By regulating these substrates, ADAM10 is involved in endothelial permeability regulation, leukocyte migration, transactivation of cancer cells, fibrogenesis, immune responses, and infectious diseases." (PMID 32372373, 2021). "The metalloproteinase ADAM10 critically contributes to development, inflammation, and cancer and can be controlled by endogenous or synthetic inhibitors." (PMID 32372373, 2021). "It will be important to understand Tspan15′s ADAM10-dependent role, for example via shedding of N-cadherin or novel substrates, and ADAM10-independent role, via NF-κB signaling, in different cancers to realize optimal targeting strategies." (PMID 34201472, 2021).